CT45A9 (cancer/testis antigen family 45 member A9)
Tractability: PROTAC: ubiquitination databases record sites on it.
Gene: Protein-coding gene on chromosome X (135,863,418 to 135,871,812, reverse strand). Ensembl gene ENSG00000270946.
Subcellular location (Human Protein Atlas): Nucleoli; Nucleoplasm
Homologues: Orthologues: rat Ct45a9 (29% identical), mouse Ct45a (27% identical), Caenorhabditis elegans ints-6 (17% identical), Drosophila melanogaster IntS6 (16% identical). Paralogues in human: CT45A2 (100% identical), CT45A8 (100% identical), CT45A3 (98% identical), CT45A1 (98% identical), CT45A5 (98% identical), CT45A6 (98% identical), CT45A7 (98% identical), CT45A10 (95% identical), SAGE1 (35% identical), INTS6L (32% identical), INTS6 (26% identical).